NDRG2 (NDRG family member 2)
Diseases named in the same sentence as NDRG2 in open-access papers (continued):
Sharing a sentence is not in itself a finding about the gene and the disease.
cancer (continued). "Our work also identified that NDRG2 exerts anti-cancer effects under conditions that mimic the microenvironment of solid tumors, which include glucose deprivation and hypoxia." (PMID 25061501, 2014). "NDRG2 was shown to inhibit the cancer cell metastasis through the attenuation of active TGF-β production or through the suppression of nuclear factor κB activity." (PMID 25061501, 2014). "Although evidence that supports anti-cancer and antimetastasis functions of the NDRG2 gene is expanding, NDRG2 function in the context of the metabolism of solid tumors remains uncertain." (PMID 25061501, 2014). "The overexpression of NDRG2 is able to enhance cell apoptosis, inhibit cell proliferation and suppress angiogenesis in many malignant tumours." (PMID 24636131, 2014). "Although evidence for the anti-cancer effects of NDRG2 is expanding, the functions of NDRG2 in metabolism field remain uncertain." (PMID 25061501, 2014). "Further studies have found that NDRG2 is able to inhibit proliferation and enhance apoptosis in many malignant tumors." (PMID 23800335, 2013). "N-myc downstream-regulated gene 2 (NDRG2) has been documented to be a pro-differentiative and anti-proliferative gene in cancer research." (PMID 23451161, 2013). "NDRG2 was documented to be a pro-differentiative and anti-proliferative gene in previous cancer research." (PMID 23451161, 2013). "As a gene to regulate downstream of Myc, NDRG2 expression has been confirmed to be reduced in many types of carcinomas, including thyroid cancer, liver cancer, meningioma, pancreatic cancer and prostate cancer." (PMID 24146910, 2013). "An increasing number of reports showed that the level of NDRG2 was reduced in many kinds of malignant tumor comparing to the normal counterpart and that NDRG2 level was an independent prognostic factor for cancer patients." (PMID 22920753, 2012). "Several studies have shown that NDRG2 mRNA is down-regulated or undetectable in various human cancers and cancer cell-lines." (PMID 21226903, 2011). "Overexpression of NDRG2 protein in cancer cell-lines results in a marked reduction in cell proliferation, although the precise mechanisms are unclear." (PMID 21226903, 2011). "By hybridising a CPA with a radioactive labelled probe it was possible to examine the levels of NDRG2 mRNA in 19 different human cancers, distributed as 154 paired tissue samples, and 9 different cell lines." (PMID 21226903, 2011). "Inhibition of cell proliferation by overexpression of NDRG2 in malignant cancer cells has also been reported." (PMID 22043305, 2011). "Our finding is consistent with the studies that NDRG2 reduces the proliferation of many kinds of cancer cells." (PMID 22043305, 2011). "NDRG2 was lately reported to be involved in hypoxia-induced apoptosis or fas-mediated cell death in different cancer cell types." (PMID 20673333, 2010). "Specifically, NDRG2 mRNA was down-regulated or undetectable in several human cancers, and over-expression of NDRG2 inhibited the proliferation of cancer cells." (PMID 18940011, 2008). "By pairwise comparison with Bonferroni's correction, we found a statistically significant increase of Ndrg2 expression in normal thyroid compared to carcinomas." (PMID 18940011, 2008). "As a gene that is regulated downstream of Myc, NDRG2 expression has been shown to be reduced in many types of carcinomas." (PMID 18940011, 2008). "We first observed the different expression profiles of Ndrg2 in a thyroid tissue array using immunohistochemistry, and we found low expression levels of Ndrg2 in the carcinomas, compared with normal tissue." (PMID 18940011, 2008). "It has recently been shown that NDRG2 mRNA is down-regulated or undetectable in several human cancers and cancer cell-lines." (PMID 17935612, 2007). "Several studies have suggested that NDRG2 mRNA is down-regulated or undetectable in a number of human cancers and cancer cell-lines." (PMID 17935612, 2007).
cancer (continued). "Our results are in agreement with that observed for other cancer types where NDRG2 expression is reduced in high-grade compared to low-grade tumors." (PMID 17935612, 2007). "Our results suggest that NDRG2 down-regulation correlates with the progression of dysplastic tissue to carcinoma." (PMID 17935612, 2007). "In fact, NDRG2 has been observed to be downregulated in several cancer types." (PMID 40378957, 2025). "Collectively, our findings demonstrated that NDRG2 might have a crucial role in preventing the suppressive activity of cancer cells on T cell proliferation by modulating PD-L1 expression." (PMID 34885221, 2021). "Meta-analysis of NDRG2 and clinicopathological features in cancer patients." (PMID 33031336, 2020). "Based on our previous findings that the diminished NDRG2 expression in cancer cells is predominantly due to transcriptional repression of its promoter by high levels of c-Myc 38, we suggest that NDRG2 and c-Myc can form a feedback loop, which is involved in the rewiring of glutamine metabolism." (PMID 33162818, 2020). "Considering the heterogeneity between studies, subgroup and mete-regression analyses were conducted by focusing on study region, cancer type, clinical stage, sample size, the proportion of patients with low NDRG2 expression, and analysis method to explore sources of heterogeneity for OS." (PMID 33031336, 2020). "Additional suppressive mechanisms of Dp44mT and DpC on matrix metalloproteases (MMPs) relate to their ability to up-regulate the metastasis suppressors N-myc downstream regulated gene-1 (NDRG1) and NDRG2, which down-regulate MMPs that are crucial for cancer cell invasion." (PMID 32948029, 2020). "Collectively, the expression of NDRG2 is reduced within human tumors, while its overexpression suppresses the capacity of cancer cells to proliferate, migrate, metabolize and invade; NDRG2 expression levels are negatively correlated with human cancer clinical and pathological conditions." (PMID 32345304, 2020). "Therefore, our meta-analysis showed that decreased NDRG2 expression was statistically correlated with poor prognosis in cancer patients." (PMID 33031336, 2020). "Regarding clinical stage subgroup analysis, a significant relationship was found between NDRG2 expression and prognosis in patients with cancer stages I-IV (HR = 1.74, 95% CI: 1.49–2.02, P < .001), others (HR = 1.65, 95% CI: 1.30–2.10, P < .001), and NR (HR = 12.29, 95% CI: 5.12–29.50, P < .001)." (PMID 33031336, 2020). "The significance of this finding is that coordinated expression changes amongst clustered genes is a common evolutionary feature, for example in both normal development (Hox genes) and also in the evolution of malignancy in cancer cells (HSP1 regulation of genes such as NDRG2 and TPD5234)." (PMID 30837567, 2019). "Together, these studies highlight the interplay between miRNAs and NDRG2 function in cancer cells." (PMID 31138100, 2019). "Lastly, they demonstrate that NDRG2-deficient but not WT TAMs co-cultured with cancer cell lines without direct cellular contact (in transwell inserts) promote cancer cell migration, colony formation and invasion." (PMID 29463798, 2018). "A large volume of data has shown that NDRG2 can inhibit cancer cell proliferation." (PMID 29445150, 2018). "For patient 9, other effective factors might involve in the expression of NDRG2 during the cancer progression." (PMID 30206227, 2018). "Thus, the induction of BMP-4 by NDRG2 inhibits the metastatic potential of cancer cells, specifically by suppressing MMP9 activity." (PMID 26506239, 2016). "Positive correlations between the expression of E-cadherin and NDRG2 have been observed in cancer." (PMID 26506239, 2016). "In this section, we focus on the regulation of NDRG2 expression in cancer." (PMID 26506239, 2016). "Furthermore, the enforced expression of NDRG2 in cancer cells suppressed phosphorylated AKT via the dephosphorylation of PTEN through the recruitment of PP2A15." (PMID 26269411, 2015).
cancer (continued). "While the methylated frequency of Ndrg2 in non-cancer controls were 4.0% (5/125)." (PMID 25823664, 2015). "This study aimed to examine whether NDRG2 participates in glycolysis and glutaminolysis in cancer cells, and to clarify the molecular mechanism about NDRG2 regulation of glycolysis and glutaminolysis." (PMID 26317652, 2015). "N-myc downstream regulated gene 2 (Ndrg2) is a candidate suppressor of cancer metastasis." (PMID 25823664, 2015). "Indeed, in normal tissue and cancer tissue, the means of immunoreactivity score of NDRG2 IHC staining were 6.03 and 1.97, respectively, and the means of immunoreactivity score of GLUT1, IHC Staining were 3.13 and 6.53, respectively." (PMID 24636131, 2014). "Previous studies have shown that NDRG2 was highly expressed in adult brain and skeletal muscle and almost undetectable in some human cancer lines, suggesting that it may play important functions in different tissues." (PMID 23800335, 2013). "Accumulated evidence indicates that NDRG2 is down-regulated or undetectable in many human cancers." (PMID 23800335, 2013). "RT-PCR and Western blot were used to detect expression of NDRG2, Bcl-2 and Bax in cancer cells." (PMID 22920753, 2012). "As a resistance regulator, NDRG2 may be re-activated or up-regulated to promote cancer cell survival during or after chemotherapy/radiotherapy." (PMID 22920753, 2012). "Since MYC is known to be either over-expressed or amplified in many human cancers, it could be responsible for the decreased levels of NDRG2 mRNA." (PMID 21226903, 2011). "Expression of NDRG2 mRNA is reduced in many different human cancers." (PMID 21226903, 2011). "Previous results have shown that NDRG2 expressed differentially in normal and cancer tissues." (PMID 18940011, 2008). "NDRG2 levels are also reduced in several cancer types and cell-lines." (PMID 17935612, 2007). "Therefore, it is likely that an inhibitor that specifically induces synthetic lethality in NDRG2low cancer cells may have a cancer-specific effect and avoid the side effects in normal cells that maintain NDRG2 expression." (PMID 38474089, 2024). "Furthermore, meta-regression demonstrated that study region (P = .517), cancer type (P = .074), clinical stage (P = .080), sample size (P = .428), the proportion of patients with low NDRG2 expression (P = .294), and analysis method (P = .238) were not able to explain the source of heterogeneity." (PMID 33031336, 2020). "In addition, overexpression of NDRG2 inhibited cellular traits thought to be cancer promoting." (PMID 29463798, 2018). "NDRG2 is a novel tumor suppressor gene and may play an important role in cancer." (PMID 25061501, 2014). "Interestingly, NDRG2 has been found to be deregulated in many kinds of human malignant tumors." (PMID 22920753, 2012). "It was also reported that restoration of NDRG2 could inhibit proliferation of cancer cells." (PMID 22920753, 2012). "In addition, P-glycoprotein and multidrug resistance protein, two transporters associated with cancer drug resistance including cisplatin resistance, were not influenced by NDRG2 in Hela cells." (PMID 22920753, 2012). "It would be interesting in future studies to examine whether the different splice forms of NDRG2 are under differential regulation, which could explain the mixed expression results observed in some cancer types and shed light on the possible function of this protein." (PMID 21226903, 2011). "Northern and dot blot analysis demonstrated that NDRG2, NDRG3, and NDRG4 are highly expressed in adult human brain and almost undetectable in eight human cancer cell lines (HL-60, HeLa S3, K-562, MOLT-4, Raji, Daudi, SW480, and A549)." (PMID 40378957, 2025). "Along with other cell-cycle inhibitors, such as PSCA, NDRG2 and SLURP1, they were downregulated in HNSCC, aligning with the hyper proliferative nature of cancer cells." (PMID 37686696, 2023).
cancer (continued). "NDRG2, another member of NDRG family which includes four members NDRG1-4, was reported to be significantly decreased in human cancers, and in GC, H. pylori silenced Ndrg2 by activating the NF-κB pathway and up-regulating DNMT3b, promoting GC progression." (PMID 34616614, 2021). "Evidence provided indicated that miR-139-5p and miR-483-5p target N-Myc downstream-regulated gene 4 (NDRG4) and NDRG2, respectively, and that overexpression of either NDRG4 or NDRG2 inhibits the invasive capacity of cancer cells." (PMID 33435156, 2021). "Thus, NDRG2 may be potentially used as a cancer therapy target." (PMID 33031336, 2020). "Collectively, our findings highlight the role of NDRG2 in the regulation of TAM polarization and its function in promoting cancer liver metastasis." (PMID 29445150, 2018). "Collectively, our study highlights the important role of NDRG2 in the regulation of TAM polarization and its function in promoting cancer liver metastasis." (PMID 29445150, 2018). "Among other genes that were clustered with STS were several genes with ubiquitous expression in the normal tissues and documented overexpression in cancers: SLC26A6, TOMM40L, AKR1B1, NDRG2 and DGAT1 (based on TCGA data)." (PMID 29088719, 2017). "Therefore, NDRG2 up-regulation may be a promising therapeutic strategy for the treatment of cancer." (PMID 26506239, 2016). "Therefore, NDRG2 might be a potential therapeutic target in targeted cancer therapy." (PMID 26317652, 2015). "Among these candidates, six genes (RhoGDI1, ALCAM, FOXJ2, FOXO3, NDRG2 and SOX11) were involved in the suppression of cancer metastasis." (PMID 26460549, 2015). "However, the role and molecular mechanism of NDRG2 in cancer metabolism remains unclear." (PMID 26317652, 2015). "And NDRG2 overexpression or Dp44mT also inhibited the TGF-β/SMAD pathway, which can activate the EMT in cancer cells." (PMID 25261367, 2014). "Conversely, a significant correlation was found between the NDRG2 methylation and the AJCC stage of the cancer (Z test, p < 0,05)." (PMID 19257893, 2009). "The silencing of PRMT5 or MEP50 expression with each specific shRNA impaired cell proliferation and the stabilization of the HSP90 client proteins AKT and NEMO in NDRG2low ATL and cancer cell lines, but not in NDRG2-expressing cell lines." (PMID 38474089, 2024). "Additionally, N-Myc downstream-regulated gene 2 (NDRG2) protein is a tumor suppressor and a SUMO target, which is frequently downregulated in several cancer types." (PMID 35887358, 2022). "When with chronic disease or cancer, COL1A1 and α-SMA were enhanced, but NDRG2 was suppressed." (PMID 35836988, 2022). "In a series of experimental metastasis experiments, the authors find that transplanting WT cancer cell lines into WT or NDRG2 knockout (KO) mice leads to reduced metastatic burden in the liver in the absence of NDRG2." (PMID 29463798, 2018). "There is a negative correlation between NDRG2 expression levels and the clinical and pathological status of human cancer." (PMID 26506239, 2016). "NDRG2 inhibited glucose transporter 1, and three key regulatory enzymes HK2, PKM2 and LDHA in glycolysis, NDRG2 also inhibited glutamine transporter ASCT2 and glutaminase GLS1 in glutaminolysis, along with the inhibition of c-Myc in cancer cells." (PMID 26317652, 2015). "Additionally, the down-regulation of NDRG2 expression promotes the inactive phosphorylated form of PTEN, which results in constitutively active PI3K/AKT signaling in various cancer cell types." (PMID 26269411, 2015). "Therefore, PP2A-activating compounds may be effective in cancers with functional NDRG2 and may synergize with PRMT5 inhibiting compounds, while NDRG2 deletions may render this strategy ineffective." (PMID 35118387, 2022).
cancer (continued). "Therefore, we screened TF, proto-oncogenes, tumor suppressor genes, and other TAG from the genes adjacent to aberrant DNA methylation sites, of which multiple known cancer related genes, including MYC, DDR1, MEF2C, NDRG2, SIX1, TNFRSF10B and TSGA10, had HyperM phenomena." (PMID 26046465, 2015). "In bresat cancer, STAT3 activation by EGF treatment induced higher Snail expression and the high expression level of snail was reversed by N-myc downstream-regulated gene 2 (NDRG2) through inhibits STAT3 binding to the Snail promoter and subsequently inhibit the EMT process and cancer progression." (PMID 26631279, 2015). "However, the detailed mechanisms for the anti-cancer effects of NDRG2 are not well elucidated and further investigation is required." (PMID 25261367, 2014). "Furthermore, immunoblotting data revealed that NDRG2 protein expression in cancer samples was much lower than that in the paired adjacent normal tissue." (PMID 24636131, 2014). "The 19 different cancer forms did not all show unidirectional changes in NDRG2 mRNA levels." (PMID 21226903, 2011). "Until now, a mechanism for the inactivation of NDRG2 in cancer cells has not been described." (PMID 20673333, 2010). "The results of our study demonstrated decreased NDRG2 mRNA expression levels in PTC, when compared to macroscopically unchanged thyroid tissue, which may point to the potential role of NDRG2 in the development and progression of cancer in question." (PMID 20804549, 2010). "However, whether NDRG2 can be utilized as a biomarker for other types of cancer, with or without other molecules, requires additional research." (PMID 26506239, 2016). "Further, the significant negative correlation of NDRG2 and ASCT2 mRNA expression levels was observed in the tissues of all cancers in both TCGA and GTEx datasets, confirming our proposal that NDRG2 suppresses ASCT2 expression in transcriptional level." (PMID 33162818, 2020). "However, unlike NDRG1 and NDRG2, which are widely known as tumor suppressor genes, the role of NDRG3 in cancer is still inconclusive." (PMID 27589737, 2016).
infection (7 papers, 2011 to 2026). The state of being infected such as from the introduction of a foreign agent such as serum, vaccine, antigenic substance or organism. "Fluorescence microscopy confirmed successful spinal cord infection and RT‐qPCR assay was performed to verify robust NDRG2 overexpression in the SDH with high infection efficiency." (PMID 41501608, 2026). "Western blot analysis revealed that the expression of Ndrg2 protein in Ad-NDRG2-infected cells markedly increased by 48 h after infection." (PMID 22043305, 2011). "Morphological changes observed in the NDRG2-infected cells included an initial cellular stretching, followed by a fibroblast-like appearance 12 h after infection." (PMID 22043305, 2011). "The infection efficiency of Ad-NDRG2 in Eca-109 cells was also examined." (PMID 23800335, 2013). "Compared to the Ad-LacZ group (the negative control), the expression of NDRG2 was successfully increased in Eca-109 cells after infection with Ad-NDRG2." (PMID 23800335, 2013).
nervous system diseases (3 papers, 2013 to 2023). "It was found that NDRG2 as a marker protein for brain astrocytes was implicated in several neurological diseases." (PMID 37373150, 2023). "Additionally, NDRG2, principally expressed in the astrocytes of the central nervous system, is regarded to be a crucial regulator during the occurrence and development of neurological diseases, ranging from glioma to stroke, neurodegenerative diseases, and psychiatric disorders." (PMID 37373150, 2023).
neurodegenerative disease (1 paper, 2025). A disorder of the central nervous system characterized by gradual and progressive loss of neural tissue and neurologic function. "Moreover, the downregulated key candidates, such as Crh and Ndrg2, were related to neurodegenerative diseases." (PMID 40420177, 2025).